ICAM1 (intercellular adhesion molecule 1)
Diseases named in the same sentence as ICAM1 in open-access papers (continued):
Sharing a sentence is not in itself a finding about the gene and the disease.
melanoma (continued). "A research of melanoma revealed that tumor cells synthesized IL-8 to upregulate the expression of β2 integrin on neutrophils, thus enhancing the neutrophil–melanoma cells' interaction with ICAM-1." (PMID 30944838, 2019). "Loss of ICAM-1 protein and mRNA expression was a strong prognosticator of diminished survival in BRAF/NRAS mutant melanoma." (PMID 30116025, 2018). "We then imaged co-cultures of the target melanoma cells with OT-I T-cells that were pre-cultured on uncoated substrates or on substrate-immobilized CCL21 + ICAM1." (PMID 29942308, 2018). "Specifically, we injected 5 × 105in vitro-activated OT1 T cells intratumorally into B16-VEGFC mouse melanoma tumors [with intense lymphatic vascularization] that had been pre-treated 8 h earlier with an ICAM-1 blocking antibody." (PMID 30258446, 2018). "B16-melanoma cells express ICAM-1 on their surfaces at significantly lower (10-fold less) levels than T cells, in accordance with what had already been described." (PMID 30258446, 2018). "In our case, B16 mouse melanoma cells expressed significantly dimmer ICAM-1 than leukocytes or endothelial cells, even under inflammation." (PMID 30258446, 2018). "We further tested ICAM-1 expression on our in-house designed TMA of paired melanoma specimens from different disease stages, in order to neutralize potential bias of inter-patient variations." (PMID 29245925, 2017). "An alternative explanation is that soluble ICAM-1, shed from melanoma cells, competes with membrane-bound ICAM-1, thus preventing the interaction and destruction of tumor cells by effector cells." (PMID 29245925, 2017). "Several possible mechanisms have been suggested to explain this contradiction; ICAM-1 on melanoma cells forms aggregates with leukocytes, allowing their dissociation from the tumor and ultimately their metastatic spread." (PMID 29245925, 2017). "Human melanoma cells have been found to express a number of cell adhesion molecules, among them Intercellular adhesion molecule 1 (ICAM-1), which mediates their interaction with leukocytes." (PMID 29245925, 2017). "The expression pattern of ICAM-1 in melanoma was studied more than two decades ago, mainly in cell lines or in unmatched melanoma specimens." (PMID 29245925, 2017). "On the other hand, several studies suggested the involvement of ICAM-1 in melanoma progression and prognosis." (PMID 29245925, 2017). "In this work, we analyze the expression of ICAM-1 during melanoma development and progression using low passage primary melanocyte and melanoma cultures and two progression tissue microarrays." (PMID 29245925, 2017). "Human ICAM-1, when transfected into a mouse melanoma cell line, was reported to function in both cell adhesion and co-stimulation of lymphokine-activated killer (LAK) T cells." (PMID 28837681, 2017). "This suggests that melanoma cells upregulate ICAM-1 in early stages of metastasis to enable at least regional spread." (PMID 29245925, 2017). "This is in accordance with studies on colon carcinoma and melanoma, demonstrating significantly suppressed ICAM-1 and VCAM-1 expression, which have been shown to contribute to decreased leukocyte adhesion in vivo." (PMID 26943029, 2016). "We show that ADAR1, in an editing-independent manner, regulates the biogenesis of miR-222 at the transcription level and thereby Intercellular Adhesion Molecule 1 (ICAM1) expression, which consequently affects melanoma immune resistance." (PMID 26338962, 2015). "Both melanoma cells and endothelial cells express ICAM-1 (intercellular adhesion molecule) on their surfaces." (PMID 26366568, 2015). "Blocking ICAM-1 expression on the melanoma cells and separately on the endothelial cells both resulted in a significant decrease in the number of melanoma cell extravasations." (PMID 26366568, 2015). "For example, knockdown of ICAM-1 reduced the invasiveness of prostate cancer cells and depletion of ICAM-1 inhibited melanoma lung metastasis." (PMID 26503469, 2015).
melanoma (continued). "In line with previous reports, transfection of miR-222 precursor into melanoma cells reduced ICAM1 at the post-transcriptional level and enhanced the resistance to TIL-mediated killing, similar to the effect of ADAR1 knockdown." (PMID 26338962, 2015). "We show that ADAR1, in an editing-independent manner, transcriptionally regulates the biogenesis of miR-222 and thereby Intercellular Adhesion Molecule 1 (ICAM1) expression, which consequently affects melanoma immune resistance." (PMID 26338962, 2015). "Remarkably, the enhanced killing of ADAR1-transfected melanoma cells was significantly reduced by a blocking anti-ICAM1 mAb, in a dose dependent manner, while only mild reduction in killing of control cells was observed following ICAM1 blocking." (PMID 26338962, 2015). "Altogether, these results suggest that HIFU increases the expressions of CD86 and ICAM-1 in melanoma tumor likely through miRNA." (PMID 26485753, 2015). "The melanoma cell in the model expresses ICAM-1 molecules on its surface, and the PMN expresses the β-2 integrins LFA-1 and Mac-1." (PMID 26366568, 2015). "Likely, melanoma cells induce ICAM-1 expression on untreated ECs and use the LFA-ICAM-1 receptor couple to incorporate in the endothelium." (PMID 25275457, 2014). "The intercellular adhesion molecule-1 (ICAM-1) (CD54) was found to be expressed on primary melanoma cells in all patients (n = 6) examined." (PMID 24489649, 2014). "Conversely, the potential involvement of ICAM-1 expression in cancer invasion and metastasis was reported in melanomas, and pancreatic, lung, and oral cancers." (PMID 24069166, 2013). "In human melanoma cells heated from 41–43°C for 3 and 6 h, an increase on the shedding of soluble intercellular adhesion molecule-1 (sICAM-1) was found, with maximum values at 3 h." (PMID 22532856, 2012). "We therefore demonstrate that melanoma cells can cross endothelial monolayers in vitro due to the induction of ICAM-1 and LFA-1 occurring during the co-culture of melanoma and endothelial cells." (PMID 23039186, 2012). "In this report, we focused on the direct role of a major integrin, LFA-1 and its counter receptor ICAM-1 in melanoma transmigration." (PMID 23039186, 2012). "We therefore conclude that preferentially the A375 and 1205LU melanoma cell lines can transmigrate through the endothelial cells due to a binding between ICAM-1 expressed by the HUVEC cells and LFA-1expressed by tumor cells during their co-culture." (PMID 23039186, 2012). "It has previously been shown that following secretion of IL-8 in the tumor microenvironment, the PMN facilitated melanoma extravasation via the binding of β2 integrins on PMNs and ICAM-1 on melanoma cells." (PMID 23039186, 2012). "All three melanoma cell lines express ICAM-1 and LFA-1 in the presence of conditioned medium from HUVEC cells." (PMID 23039186, 2012). "Our data further suggest a role of LFA-1 and ICAM-1 in the formation of melanoma cell clumps enhancing tumor cell transmigration." (PMID 23039186, 2012). "Based on these findings, CVA13, CVA15 and CVA18 were evaluated as potential candidates for the ICAM-1 targeted oncolytic therapy of malignant melanoma." (PMID 21241513, 2011). "As CVA13, CVA15, and CVA18 utilize ICAM-1 for virus-cell entry, these viruses were evaluated for their oncolytic activity against the panel of melanoma cells and the control cell line RD-ICAM-1." (PMID 21241513, 2011). "Previously we have shown that Coxsackievirus A21 (CVA21) can selectively infect and destroy in vitro cultures of malignant melanoma cells that characteristically over-express intercellular adhesion molecule-1 (ICAM-1) and/or decay accelerating factor (DAF)." (PMID 21241513, 2011). "As a first approach, surface levels of ICAM-1 were examined on the melanoma cell lines SK-Mel-28, SK-Mel-RM, ME4405 and MV3." (PMID 21241513, 2011).
melanoma (continued). "LPS stimulation also increased the retention of B16F1 melanoma cells in the liver between 8–24 h, especially in the terminal portal venule region presumably through increased expression of adhesion molecules, ICAM-1 and VCAM-1." (PMID 16336680, 2005). "The arrest of B16F1 melanoma cells in the liver sinusoids (following mesenteric vein injection) induced focal expression of VCAM-1 and more diffuse expression of ICAM-1 around the melanoma cell arrest sites." (PMID 16336680, 2005). "LPS did not significantly alter the expression of VLA-4 (very late antigen-4, counter receptor of VCAM-1) or LFA-1 (leukocyte functional antigen-1, counter receptor of ICAM-1) on melanoma cells either in vivo or in vitro." (PMID 16336680, 2005). "Serum soluble interleukin-2 receptor (sIL-2R), intercellular adhesion molecule-1 (sICAM-1) and interleukin-10 (IL-10) have each been reported as useful markers for melanoma progression." (PMID 10970683, 2000). "Our in silico analysis on The Cancer Genome Atlas and ex vivo experiments on human primary melanoma samples revealed that increased ICAM-1 expression positively correlated with increased immunogenicity of human melanoma cells and correlated with increased immune cell infiltration." (PMID 39867570, 2025). "A recent study found that blocking the expression of ICAM1 reduced both tumor size and metastasis of melanoma in older mice, suggesting ICAM1 could be a potential treatment target in elder patients with melanoma." (PMID 40864319, 2025). "Collectively, these results describe that DNMTi-induced ICAM-1 upregulation correlates with a modulation of melanoma secretome in inducing the secretion of the T-cell chemokines CXCL9 and CXCL10 and with the survival positive predictor 12-chemokine melanoma signature." (PMID 39867570, 2025). "Expression of these adhesion molecules, especially ICAM1, might be directly involved in enhanced melanoma retention and hepatic metastasis as we demonstrate inhibition of melanoma cell retention by anti-ICAM1 antibody treatment." (PMID 39875968, 2025). "In addition, the overexpression of intercellular adhesion molecule 1 (ICAM-1) and PD-L1 on melanoma-derived exosomes facilitates the binding to LFA-1 and PD-1 on T cells, respectively, mediating immune suppression." (PMID 40872479, 2025). "Collectively, these results show that among the selected subset of melanoma surfaceome proteins, DNMTi-induced ICAM-1 upregulation is the most strongly modulated epitope after administration of several epigenetic inhibitors targeting the main epigenetic mark classes." (PMID 39867570, 2025). "In contrast, others showed that ICAM-1 upregulation may have detrimental effects in supporting melanoma extravasation across the endothelium and in shaping the metastatic niche." (PMID 39867570, 2025). "Of note is a high saturation of ICAM1 in melanoma exosomes relative to the cell lysate." (PMID 40805206, 2025). "Furthermore, β2 integrins (CD18) on IL-8+ neutrophils interact with ICAM-1 on melanoma cells, anchoring tumour cells to vascular endothelium and facilitating extravasation." (PMID 41451221, 2025). "However, it also increases the expression of various tumour markers, including HLA-DR, A.1.43, and -DQ ICAM-1 which are markers in advanced melanomas." (PMID 38268823, 2024). "The dual therapeutic benefits of ICAM1‐ADC might pave the road for clinical development of ADC for melanoma." (PMID 38874532, 2024). "Further, decitabine could enhance antitumor efficacy of ICAM1‐ADC with multiple mechanisms, mainly including synergistically boosting anti‐tumor immunity; upregulating ICAM1 expression on melanoma cell; enhancing tumor penetration of ICAM1‐ADC." (PMID 38874532, 2024). "Indeed, blocking ICAM1 with suitable antibodies reduces tumor size and distant metastasis in older mice with melanoma." (PMID 38760832, 2024). "identify that ICAM1‐ADC exerted potent antitumor activity in melanoma." (PMID 38874532, 2024).
melanoma (continued). "In addition, mouse melanoma tumors that relapse after adoptive T cell therapy show decreased content of ICAM-1 mRNA." (PMID 38228372, 2024). "To evaluate the efficacy of ADCs with different MoAs for melanoma, we evaluated two in‐house ICAM1‐ADCs (namely I1‐MMAE and I1‐DXd) previously developed by us via conjugating monoclonal ICAM1 antibodies with two clinically proven linker and payload combinations: GGFG‐DXd and MC‐Vc‐Pab‐MMAE." (PMID 38874532, 2024). "Moreover, we also investigated the impact of DAC pre‐treatment on the melanoma cell internalization of ICAM1 antibodies." (PMID 38874532, 2024). "However, the roles of CSTB, GBF1, PML and ICAM1 in melanoma development were still unclear, which deserved to further exploration." (PMID 37217516, 2023). "In particular, the interaction between LFA-1/ICAM-1 and melanoma cells may activate signaling pathways, enhancing the invasive and metastatic abilities of melanoma cells." (PMID 37388230, 2023). "Furthermore, highly expressed and active ICAM-1 promoter responsive genes were identified in melanoma cells." (PMID 37875556, 2023). "In addition, TNF-α administration fostered the infiltration of CD8+ T cells into tumor tissues and repressed melanoma growth in dysbiotic mice by increasing the expression level of ICAM-1 in the tumor vasculature." (PMID 36726985, 2022). "IL6 activates the antitumor immunity, regulates the secretion of the anti-inflammatory cytokine IL10 in the melanoma cells via the PI3K and ERK related pathways, and promotes the E/P-selectin- and ICAM-1-dependent extravasation of the cytotoxic T cells in melanoma lesions in vivo." (PMID 35327461, 2022). "Given the role of ICAM-1 shedding during the transendothelial migration of lymphocytes and myeloid cells, it is expected that the shedding also plays a role in the transendothelial migration of melanoma." (PMID 36132127, 2022). "Furthermore, ICAM1 expression is involved in melanoma cell infiltration into liver upon their injection into the tail vein of mice." (PMID 36248978, 2022). "Moreover, it was shown that in melanoma patients, the presence of ICAM1 correlates with a worse prognosis." (PMID 35538545, 2022). "Melanoma cells that express ICAM-1 and therefore could be infected showed significantly increased cell death upon infection with CVA21 in a dose-dependent manner, whereas cells that could not be infected did not have an appreciable increase in cell death." (PMID 34503272, 2021). "In view of the important role played by endothelial ICAM‐1 in mediating the adhesion of melanoma cells to the endothelium, ICAM‐1 expression was measured in BEC treated with MCM derived from ALDOC overexpressing MBM cells and in BEC that were treated with MCM of control MBM cells." (PMID 33274599, 2021). "A panel of human melanoma cell lines were assessed for expression of the CVA21 receptor ICAM-1." (PMID 34503272, 2021). "Interestingly, we found that grapefruit-derived NVs and MVs reduce ICAM 1 expression, possibly limiting the uncontrolled adhesion capability of melanoma cells." (PMID 33371199, 2020). "Intercellular adhesion molecule-1 (ICAM-1) is expressed on the surface of melanoma cells." (PMID 33042821, 2020). "miR-222 directly interact with 3’UTR of the Intracellular Adhesion Molecule 1 (ICAM1) mRNA which, consequently, affects melanoma immune resistance by rendering melanoma cells more resistant to TIL-mediated killing mainly due to their ability to cross endothelial vessels and infiltrate tumor tissues." (PMID 32604720, 2020). "Similarly, in mouse models of melanoma, melanoma-specific expression of ICAM1 facilitated tumor cell-neutrophil interactions via β2 integrin on neutrophils, which facilitated attachment to the endothelium in the secondary lung microenvironment." (PMID 31497019, 2019). "Additionally, the protein expression levels of metastasis-associated genes (such as MMP2/9, ICAM-1 and VCAM-1) in melanoma cells were suppressed by CLQ treatment." (PMID 31138783, 2019).
melanoma (continued). "One study, performed in C57BL mice bearing ICAM-1 expressing B16 melanoma tumours, showed that the therapeutic effect of eight intratumoural injections of CVA21 is increased when combined with four intraperitoneal deliveries of antimouse-PD-1 antibodies than either therapy alone." (PMID 31100962, 2019). "For example, in vitro microfluidic models of the human microvasculature have shown that LPS-stimulated neutrophils and melanoma cells form aggregates under flow conditions, and arrest on the endothelium in part due to neutrophil-endothelial cell interactions via ICAM1." (PMID 31497019, 2019). "The immunomodulatory activity of different DHAs on the constitutive expression levels of HLA class I antigens and the co-stimulatory molecule, ICAM-1, was evaluated in 14 melanoma cell lines and 10 hematological cancer cell lines treated with 1 μM guadecitabine, DAC or AZA, by flow cytometry." (PMID 30581389, 2018). "Indeed, we observed a potential link between the expression intensity of ICAM-1 in primary melanoma and progression to Stage III." (PMID 29245925, 2017). "This renders the melanoma cells more resistant to T-cells by lowering ICAM-1 protein expression." (PMID 29245925, 2017). "ICAM-1 expression has been shown to correlate with the metastatic potential of melanoma." (PMID 29245925, 2017). "Also, we have shown aspirin can effectively inhibit TNF-α -induced upregulation of NF-kappaB and ICAM-1 expression during in vitro migration and invasion of human melanoma cells." (PMID 27270229, 2016). "In particular, LFA-1 has been extensively described as having an essential role in leukocyte extravasation at cancer sites, whilst other studies have suggested a requirement for LFA-1/ICAM-1 interactions between melanoma and endothelial cells to aid transmigration of tumour cells." (PMID 27447568, 2016). "In addition, we find that anti-CD40 antibodies and sunitinib therapy up-regulate ICAM-1 in B16.F10 melanoma and VCAM-1 in both models, thereby decreasing the endothelial barrier to lymphocyte recruitment." (PMID 27385210, 2016). "We next evaluated the rate of TILs and ICAM1 expression in these 22 melanoma specimens." (PMID 26338962, 2015). "Similar to melanoma cells, all melanoma cell lines expressed high levels of ICAM-1 (CD54)." (PMID 24489649, 2014). "We therefore hypothesized that melanoma-endothelial cell co-culture might induce the ICAM-1/LFA-1 ligand-receptor interaction." (PMID 23039186, 2012). "As ICAM-1 expression is often detected on melanoma cell lines, we hypothesized that clumps might assemble due to an interaction of LFA-1 and ICAM-1, and that this cell association might enhance melanoma transmigration capacities as described in some tumors." (PMID 23039186, 2012). "However, the constitutive expression of ICAM-1 on CTCs was found to promote tumor cell transendothelial migration in melanoma, pancreatic, and breast cancers." (PMID 22837985, 2012). "As exogenous inflammation molecules are not used in the transmigration assays displayed in this report, we wondered if melanoma cell lines could induce ICAM-1 expression in HUVEC cells." (PMID 23039186, 2012). "Coxsackieviruses A13, CVA15 and CVA18 are an enteroviral subset that potentially may be used to destroy malignant melanoma tumor cells because their entry receptor ICAM-1 is abundantly expressed on the surface of melanoma cells." (PMID 21241513, 2011). "A previous study revealed very high levels of ICAM-1 gene expression in melanomas." (PMID 18958307, 2008). "IL-10 has also been shown to down-regulate ICAM-1 in human melanoma cells." (PMID 15518595, 2004). "Because the data obtained from the SKCM TCGA were not derived by DNMTi-treated patients, we speculate that melanoma ICAM-1 upregulation may be linked not only to HLA I upregulation but possibly to other key APM components." (PMID 39867570, 2025).